CXCL8 (C-X-C motif chemokine ligand 8)
Diseases named in the same sentence as CXCL8 in open-access papers (continued):
Sharing a sentence is not in itself a finding about the gene and the disease.
breast tumor (continued). "Thus, hyper-activated RasG12V cooperated with inflammatory factors that were shown to be prevalent at the breast tumor microenvironment, together potentiating the release of the powerful angiogenic and tumor-promoting chemokine CXCL8 by the tumor cells." (PMID 24598028, 2014). "Noting that WT-Ras is the form of the protein that is abundant in most breast tumor cells, we asked whether it acts similarly to RasG12V, and if it is able to act alone to induce CXCL8 up-regulation." (PMID 24598028, 2014). "Therefore, CXCL1/2 and CXCL8 may act in a synergistic manner to control neutrophil trafficking to breast tumors." (PMID 40833805, 2025). "In these cells, EGF stimulation has induced the expression of CXCL8, indicating that activation of RTKs is a relevant pathway for induction of CXCL8, which may account for Ras hyper-activation in breast tumor cells that do not carry mutated Ras." (PMID 24598028, 2014). "A critical cytokine in this process is interleukin-8 (IL-8/CXCL8), which is commonly overexpressed in primary breast tumors and can stimulate both osteoclastogenesis and bone resorption, independent of other tumor-derived signals." (PMID 41596432, 2026). "The findings presented in this study indicate that oncogenic events, such as hyper-activation of the Ras pathway, exacerbate the release of pro-malignancy chemokines (e.g., CXCL8 and CCL2) by MCF-7 human breast tumor cells." (PMID 24598028, 2014). "Here, it was interesting to note that similar elevations in CXCL8 production were not evident when the partners in the co-cultures were luminal-A breast tumor cells instead of TNBC cells." (PMID 32582148, 2020). "In this respect, it was found also that fibroblast-derived SASP induced EMT in non-aggressive breast tumor cells, with direct roles of CXCL8 + IL-6 in promoting tumor cell invasiveness." (PMID 32582148, 2020). "Indeed, several studies support such a scenario: when breast tumor cell-derived supernatants promoted osteoclastogenesis, as indicated by increased generation of TRAP+ cells out of peripheral blood mononuclear cells, the process was down-regulated by inhibitors of CXCL8 or its receptors." (PMID 32582148, 2020).
delirium (65 papers, 2009 to 2026). A disorder characterized by confusion; inattentiveness; disorientation; illusions; hallucinations; agitation; and in some instances autonomic nervous system overactivity. "Univariate analysis revealed that elevated levels of CXCL10, CXCL9, and CXCL8 were linked to an increased delirium risk." (PMID 38861234, 2025). "Importantly, CXCL8 was significantly associated with the severity of delirium as assessed with the DRS-R-98 scale." (PMID 35641947, 2022). "In our research, we found higher levels of CXCL8, CXCL9, and CXCL10 to be associated with delirium in univariate analysis." (PMID 38861234, 2025). "In this respect, previous reports showed that increases in peripheral levels of C-reactive protein (CRP), interleukin-6 (IL-6), CXCL8 (IL-8), and tumor necrotic factor (TNF)-α are associated with the onset of post-operative delirium." (PMID 35641947, 2022). "Increased blood levels of CXCL8 have been noted in elderly patients with delirium." (PMID 38861234, 2025). "The first major finding of this study is that delirium and/or the severity of delirium symptoms are significantly associated with the IRS/CIRS ratio, namely positively with M1 (i.e. IL-6, CXCL8 and TNF-α), Th1 and Th17 activation and T cell growth (positively), and inversely with IL-4 and sIL-1RA." (PMID 35641947, 2022). "In univariate analysis, increased levels of CXCL8, CXCL9, and CXCL10 showed an association with delirium, although this link was not evident in the multivariate analysis." (PMID 38861234, 2025). "For example, one study showed increased IL-6, IL-2, and IL-1α levels in delirium due to septic shock, although no such increases in CRP, CXCL8 and TNF-α could be established." (PMID 35641947, 2022).
Cirrhosis (60 papers, 2009 to 2025). A chronic disorder of the liver in which liver tissue becomes scarred and is partially replaced by regenerative nodules and fibrotic tissue resulting in loss of liver function. "In AD and ACLF patients, CXCL1 and CXCL8 levels are highly elevated, even compared with those in patients with compensated cirrhosis; however, impaired neutrophil migration persists and is associated with adverse outcomes in these cohorts." (PMID 40721870, 2025). "Numerous pieces of evidence indicate a significant elevation of C-X-C motif chemokine ligand 8 (CXCL8/IL-8) in patients with ALD cirrhosis, which prompts Kupffer cell activation and leads to hepatic inflammation infiltration." (PMID 39640486, 2024). "The serum profiles of cytokines of ALD- and NAFLD-cirrhosis both displayed relatively high HGF and CXCL8 serum levels when compared to the HBV- or HCV-cirrhosis group." (PMID 36230823, 2022). "High gene expression levels of CXCL3, CXCL8, and IL1A also correlate with HCV-associated liver inflammation, cirrhosis, and HCC." (PMID 34497613, 2021). "Additionally, the release of CXCL8 is linked to the advancement of chronic liver disease, with monocytes/macrophages being the main responders to CXCL8 in cirrhosis." (PMID 38920978, 2024). "In addition to these differences, the immune profiles of ALD- and NAFLD-cirrhosis were comparable with higher levels of CXCL8 and HGF, compared to patients with viral hepatitis." (PMID 36230823, 2022). "Thus, the diagnosis of cirrhosis, hepatitis, or pancreatitis that reached about a 24% of AUD patients was associated with elevated CXCL8 concentrations." (PMID 28149283, 2016). "CXCR4 (AUC = 0.941), COL1A2 (AUC = 0.919), CCR7 (AUC = 0.878), COL1A1 (AUC = 0.853), CXCL12 (AUC = 0.848), and CXCL8 (AUC = 0.828) had similar AUC values, demonstrating that the identified hub genes exhibited a reliable discriminatory capacity as potential biomarkers for cirrhosis." (PMID 41223189, 2025). "Compared with the GRS 0–4 group, patients with cirrhosis with GRS 5–8 exhibited increased levels of MMP2 (FDR <0.05), CCL1, and CXCL8 (p <0.05)." (PMID 40995436, 2025). "In accordance with that publication, we found elevated levels of CXCL10, CXCL8 and M-CSF in serum of cirrhotic patients with HBV and HCV, and for the first time describe similar alterations in ALD and NAFLD cirrhosis." (PMID 36230823, 2022). "A previous study on cytokines in cirrhosis demonstrated that HBV- and HCV-cirrhosis affected CXCL10, CXCL8, M-CSF and TNF serum levels." (PMID 36230823, 2022). "Excluding CCL-11, higher levels of chemokines CCL-3, CCL-4, CCL-5, CXCL-8, and CXCL-10 were observed in compensated cirrhosis patients compared to fibrotic and decompensated cirrhosis patients." (PMID 29977152, 2018). "In our assessment, CXCL1 levels corresponded with HBV-cirrhosis, while CXCL8 was characteristic of non-viral etiologies." (PMID 36230823, 2022). "However, CCL1 was only associated with lean cirrhosis in this comparison, whereas CXCL8 did not exhibit statistical significance in either the lean or overweight cirrhosis groups." (PMID 40995436, 2025). "In contrast, in cirrhosis, THY1+ and THY1−ACTA2high were both present, without a distinct CXCL8+ subset." (PMID 35320046, 2022). "For example, chemotaxis towards CXCL8, CXCL1 or casein, and phagocytosis of C. albicans are not impaired in cirrhosis, which might indicate that functional defects in cirrhosis are limited to certain pathways." (PMID 37822786, 2023).
gout (60 papers, 2005 to 2025). A condition characterized by painful swelling of the joints, which is caused by deposition of urate crystals. "Several cohort studies have shown that higher CXCL8 levels in gout patients increase the risk of CVD and type 2 diabetes." (PMID 38686389, 2024). "Since IL-1β and IL6 have been linked to gout in numerous studies, our main focus was on the connection between CXCL8, CXCL1, and CXCL2 and acute gouty arthritis." (PMID 38686389, 2024). "It was demonstrated that CXCL8 levels are more highly increased than other pro-inflammatory cytokines in gout patients, and it is directly associated with neutrophil infiltration, pain, and the development of chronic gouty arthritis." (PMID 32395118, 2020). "The results showed that low expression of key genes CXCL8, PTGS2 and IL10 were risk factors for gout." (PMID 40606658, 2025). "Among 329 gout-related genes identified, CXCL8, PTGS2, and IL10 emerged as key regulators involved in cell-cell adhesion, leukocyte activation, and NF-κB signaling." (PMID 40606658, 2025). "Among these, pergolide exhibited the highest binding affinity with key gene-encoded proteins, suggesting potential therapeutic effects against gout through targeting CXCL8, PTGS2, and IL10." (PMID 40606658, 2025). "These novel biomarkers of XOI treatment effects were identified within an interactome with central gout mediators including IL-1B, CXCL8, IL6, and C5." (PMID 39426967, 2024). "In contrast to differential miR-339-5p, miR-486-5p, and miR-361-5p expression pattern, the roles of CCL2 and CXCL8 in gout patients are well known." (PMID 30854012, 2019). "Circulating IL-8/CXCL8 has potential as a unique cytokine biomarker for gout in the period between flares." (PMID 28818081, 2017). "For example, gout comorbidities and systemic inflammation with expression of pro-atherogenic cytokines IL-1β, IL-8/CXCL8, and IL-6 have the capacity to accelerate atherogenesis." (PMID 28818081, 2017). "The ability of the ceRNA network to predict miRNAs and lncRNAs upstream of CXCL8, CXCL1, CXCL2, IL-1β, and IL6 may lead to the use of a novel diagnostic and prognostic marker for gout." (PMID 38686389, 2024). "This study systematically elucidated the pivotal roles of CXCL8, PTGS2, and IL10 in gout pathogenesis, providing valuable molecular targets for therapeutic development." (PMID 40606658, 2025). "RELA and NFKB1 are the core components of the classic NF-κB signaling pathway, directly involved in the regulation of various pro-inflammatory genes (such as CXCL8 and PTGS2), driving gout-related inflammatory responses." (PMID 40606658, 2025). "The target genes of Terpine-4-ol, a main compound of ZP, were overlapped with the gouty arthritis-related genes such as NLRP3, PTGS2, CXCL8, IL6, TNF, IL1B, TLR4, and ALB." (PMID 39861092, 2024). "Previous studies have found an increased expression of various chemokines (including CXCL8, CCL3, CXCL2, and MCP-1) in stimulations with MSU crystals in experimental models of gout or in the serum of gout patients." (PMID 36979628, 2023). "CXCL8 and PTGS2 were predominantly expressed in T/NK cells and myeloid cells, while IL10 was mainly expressed in myeloid cells, with all key genes showing elevated expression in the gout group." (PMID 40606658, 2025). "In summary, CXCL8, CXCL1, and CXCL2 may be gout biomarkers, and this research may lead to novel approaches for the clinical management of individuals with gouty arthritis." (PMID 38686389, 2024). "Our findings could lead to the development of new approaches for the treatment of gout; however, the precise regulatory mechanisms of CXCL8, CXCL1, and CXCL2 in gout remain unclear." (PMID 38686389, 2024). "Dapansutrile may reduce the inflammatory response and the chemotaxis of inflammatory cells by blocking the activation of IL1B, CXCL8, and TNF for the treatment of gouty arthritis." (PMID 36105284, 2022).
gout (continued). "Indeed, increased levels of CXCL8 (IL-8), CXCL1 (KC) and CXCL10 (IP-10) have been detected in synovial fluid in patients with gouty arthritis." (PMID 27863506, 2016). "Further PPI network analysis jointly identified three key genes, CXCL8, PTGS2, and IL10, which have a high degree of connectivity in the PPI network, suggesting that they may play a core regulatory role in the pathogenesis of gout." (PMID 40606658, 2025). "These PPI network analysis results showed that the key genes CXCL8, PTGS2 and IL10 played a key regulatory role in the PPI network, suggesting that they may play an important role in the occurrence and development of gout." (PMID 40606658, 2025). "Therefore, dapansutrile may reduce the chemotaxis and activation of inflammatory cells for the treatment of gouty arthritis by blocking the activation of IL1B, CXCL8, and TNF." (PMID 36105284, 2022). "There are no publications on the involvement of these miRNAs in gouty arthritis or correlations with CCL2 and CXCL8." (PMID 30854012, 2019).
Hyperglycemia (56 papers, 2006 to 2025). An increased concentration of glucose in the blood. "In vitro, podocyte CXCL8 release was strongly enhanced during a high-glucose challenge, suggesting that hyperglycemia may trigger podocyte CXCL8 production in diabetic patients, which could in turn activate death signals through an autocrine loop and facilitate diabetic nephropathy." (PMID 40718478, 2025). "Our microarray experiments demonstrated that metformin upregulated downstream targets in VEGFA pathway; MMP16, FABP4, ROCK1, TFPI2, CXCL-8, and LY96 under hyperglycemia-CoCl2, which play a part in cell migration." (PMID 29351188, 2018). "Indeed, hyperglycemia can elevate reactive oxygen species (ROS) in fibroblasts, while increasing expression of apoptotic and pro-inflammatory genes, including (caspase 3/CASP3), CCL13, IL8/CXCL8, SERPINE1, and TNFα." (PMID 33669239, 2021).
type 2 diabetes (56 papers, 2009 to 2026). "In addition, dry eye disease is highly prevalent among patients with type 2 diabetes and has been consistently linked to increased tear concentrations of proinflammatory cytokines such as IL-6, CXCL8, and TNF-α." (PMID 41030257, 2025). "Similarly, the expression of the proinflammatory cytokine IL1B mRNA and CXCL8 showed a clear trend of increase with a high correlation to HIF1A mRNA levels in samples from type 2 diabetic patients living at high altitude." (PMID 34651203, 2022). "Despite limitations, this study demonstrates a distinctive inflammatory tear cytokine profile (elevated IL-6, CXCL8, IL-15, CCL5, VEGF) in type 2 diabetes patients, contrasting with decreased systemic inflammation." (PMID 41030257, 2025).
gastritis (55 papers, 2007 to 2025). Inflammation of the stomach. "In H. pylori infection, CXCL-8 overexpression is directly linked to gastritis and cancer propagation." (PMID 38572314, 2024). "CXCL8 recruits neutrophils but these cells cannot eliminate H. pylori infection, causing chronic neutrophil inflammation and gastritis." (PMID 34680333, 2021). "Of which, MMP9, CXCL2, CXCL8, and IL-10 were part of the 15 common genes, and these four genes are significantly upregulated between gastritis patients and normal control." (PMID 34471638, 2021). "PTGS2, NOS2, EGFR, MMP9, CXCL2, CXCL8, and IL-10 may be the important direct targets of Weibing Formula 1 in gastritis treatment." (PMID 34471638, 2021). "The presence of H. pylori infection and gastritis may lead to CXCL8 synthesis by stomach epithelial cells." (PMID 34680333, 2021). "In addition to IL-10, MMP9, CXCL2, and CXCL8 expression levels were significantly increased in gastritis patients compared with the control group, which was consistent with the GSE60427 and GSE5081 results." (PMID 34471638, 2021). "Circulating CgA levels correlate with serum inflammatory markers like C-reactive protein (CRP), procalcitonin, IL-1β, IL-6, IL-8/CXCL8, IL-17C, or TNF in conditions such as gastritis, IBD, chronic heart failure or systemic inflammatory response syndrome." (PMID 40370467, 2025). "In conclusion, the potential mechanism of Weibing Formula 1 in treating gastritis has the multicomponent, multitarget, and multiway characteristics, and PTGS2, NOS2, EGFR, MMP9, CXCL2, CXCL8, and IL-10 may be the important direct targets of Weibing Formula 1 in gastritis treatment." (PMID 34471638, 2021).
triple-negative breast carcinoma (55 papers, 2012 to 2026). An invasive breast carcinoma which is negative for expression of estrogen receptor (ER), progesterone receptor (PR), and human epidermal growth factor receptor 2 (HER2). "CXCL8 was also identified in triple-negative breast cancer as a potential druggable target, as it was found to promote paclitaxel resistance." (PMID 40299479, 2025). "NF-κB/p65 protein phosphorylated at the Ser536 residue binds the promoter of the CXCL8 gene and enhances CXCL8 expression in triple-negative breast cancers." (PMID 39905539, 2025). "Recent studies have revealed the role of CXCL8 in the progression of triple-negative breast cancer (TNBC)." (PMID 38791448, 2024). "CXCL8 promotes triple-negative breast cancer growth and development, as well as paclitaxel resistance." (PMID 36497164, 2022). "In triple-negative breast cancer, the direct targeting of CXCL8 by using the monoclonal antibody HuMax-IL8 significantly reduces PMN-MDSC infiltration to the TME and improves immunotherapy efficacy." (PMID 36091114, 2022). "It has been reported that the anti-CXCL8 monoclonal antibody abolishes the recruitment of neutrophils into tumor and increases the antitumor immunity of triple- negative breast cancer." (PMID 36091114, 2022). "Moreover, SERPINE1, CXCL5, and CXCL8 were found dramatically elevated in triple-negative breast cancer (TNBC) cell lines compared with non-triple-negative breast cancer (non-TNBC) cell lines." (PMID 33371368, 2020). "As for directly targeting CXCL8, in triple-negative breast cancer (TNBC), HuMax-IL8, a fully human monoclonal antibody that inhibits CXCL8, can significantly reduce the infiltration of PMN-MDSCs to TME and enhance the efficacy of immunotherapy." (PMID 35372515, 2022). "Triple negative breast cancer (TNBC) cells express increased levels of the pro-inflammatory and pro-angiogenic chemokine interleukin-8 (IL-8, CXCL8), which promotes their proliferation and migration." (PMID 30089134, 2018).
Alzheimer disease (54 papers, 2005 to 2025). A progressive, neurodegenerative disease characterized by loss of function and death of nerve cells in several areas of the brain leading to loss of cognitive function such as memory and language. "In the nervous system, SHP2 has been found to promote inflammation by increasing the production of CXCL‐8 (IL‐8), which has been linked to Alzheimer's disease through regulation of P38 and ERK." (PMID 36751313, 2023). "In this study, we focused on chemokine CXCL8 based on recent research implicating this chemokine in neuropathogenesis during several neurodegenerative disorders such as Alzheimer’s disease and human immune deficiency virus (HIV)-1 infection." (PMID 23029125, 2012). "Astrocyte activation and overexpression of cytokines and chemokines like IL-1β, TNF-α and CXCL8 have been associated with Alzheimer’s disease." (PMID 23029125, 2012). "Increases in IL-6, CCL2 and CXCL8 are associated with activation of perivascular macrophages and glia, and with the development of neurological diseases such as HAND, Alzheimer’s disease, Parkinsons’s or Huntington’s disease, and multiple sclerosis." (PMID 22901451, 2012). "MIP-1b (CCL4), IL-8 (CXCL8), and MCP-1 (CCL2) have all been identified as pro-inflammatory chemokines and can induce the migration of leukocytes to a desired site and have also been implicated in other inflammatory diseases such as multiple sclerosis, Alzheimer's disease, and HIV." (PMID 22359672, 2012). "Of note, both CXCL8 and CCL2 levels were found to be increased in the cerebrospinal fluid and brain tissue of Alzheimer’s disease patients and higher CCL2 levels in cerebrospinal fluid were associated with a faster rate of cognitive decline during the early stages of the disease." (PMID 34335238, 2021).